MYC (MYC proto-oncogene, bHLH transcription factor)
Diseases named in the same sentence as MYC in open-access papers (continued):
Sharing a sentence is not in itself a finding about the gene and the disease.
melanoma (continued). "Moreover, the dependency of TFIIH-CAK on the melanocyte master regulator MITF or its structural homolog c-MYC extends the conceptional idea of a CDK7-targeted treatment approach to melanoma far beyond super-enhancers as determinants of oncogenesis." (PMID 30651597, 2019). "KRAS/c-MYC dysregulation increases melanoma NC toxicity reversed by TTM." (PMID 30792807, 2019). "Additionally, as is true for many cancer types, MYC expression is related to aggressive forms of melanoma and is being investigated as a potential therapy target in melanoma." (PMID 30987032, 2019). "KRAS/c-MYC dysregulation attenuates TTM reversion of melanoma toxicity by DSF + OPT." (PMID 30792807, 2019). "Results: c-MYC and Sestrin-1 genes proved to undergo intron retention specifically in melanoma." (PMID 30795533, 2019). "Furthermore, we have validated the clinical significance of our findings by unveiling the involvement of CDK1 in MYC target genes, mTOR signaling and DNA repair pathways in patient tumors from melanoma, colon and pancreatic cancer." (PMID 31080551, 2019). "Besides, FISH analysis demonstrated that malignant melanoma, a tumor that can also be induced by UV-radiation, shows MYC copy number gain." (PMID 29765529, 2018). "In addition, there are multiple targets of MYC, LEF1, and E2F1 that are also associated with poor outcomes for melanoma patients." (PMID 29666373, 2018). "Inhibition of MYC overcomes drug resistance in BRAF-driven melanoma and other human cancers." (PMID 28152508, 2017). "Although one can observe negative correlations between MYC copy number gains and CD8 T cell estimates in melanoma (Pearson correlation: -0.18) and some other tumor types, the MYC copy number levels are also highly correlated with purity estimates (melanoma Pearson correlation: 0.33)." (PMID 28749946, 2017). "Another mechanism through which SOX10 mediates melanoma development—in cooperation with MYC—is related to the induction of a lysosomal program of gene expression: melanoma cells exploit the development of lysosomal degradation pathways to accelerate tumor growth." (PMID 29156643, 2017). "Finally, the induction of pro-apoptotic protein NOXA by bortezomib is directly dependent on the oncogene MYC in melanoma cell lines." (PMID 29134486, 2017). "Considering the reversibility of epigenetic changes, the participation of SIRT1 and other epigenetic components in reducing Mxd1 expression and in increasing MYC oncogenic activity might have prognostic and therapeutic potential in melanoma." (PMID 29383100, 2017). "Consistent with this premise, antisense oligodeoxynucleotides or the silencing of MYC by small-interfering RNA increases cisplatin sensitivity in inherently cisplatin-resistant melanoma cell lines in vitro and reduces tumor formation in xenograft models of cisplatin-resistant ovarian cancer cells." (PMID 28590415, 2017). "Taken together, our data indicate that depletion of dNTPs is one of the major causes of DNA damage and senescence in MYC-depleted melanoma cells and that maintaining high TS, RRM1 and RRM2 levels is important for C-MYC-dependent suppression of senescence programs in these cells." (PMID 23249808, 2012). "Conversely, c-MYC down-regulation resulted in an increase of cisplatin-induced apoptotic cell death in human melanoma cells, suggesting that the decisive factors influencing a cell to undergo apoptotic cell death and how c-MYC regulates this apoptotic response depend on the cell type." (PMID 21324178, 2011).
melanoma (continued). "In the context of melanoma, the loss of USP28-FBW7 complex has been identified as a significant mechanism to BRAFi in the treatment of metastatic melanoma: it causes the accumulation of oncogenic proteins, such as MYC, whose stability is normally regulated by FBW7." (PMID 40872623, 2025). "Additionally, inhibiting FAO in MYC+ melanoma cells could effectively reduce lymph node metastasis favored by MITF, which provided a potential therapeutic approach in melanoma dissemination." (PMID 40376583, 2025). "In addition, restoring the expression of c-MYC could partially restore the proliferation and migration ability of melanoma cells in the RAI14 knockdown group." (PMID 36233342, 2022). "Furthermore, it was proven that activation of Wnt/β-catenin pathway could increase the levels of p-GSK3β (Ser9), MYC and Cyr61, while MYC overexpression elevated the levels of MYC and Cyr61 in melanoma cells with circ-GLI1 silence." (PMID 32732916, 2020). "Patients with anorectal melanoma, melanoma with amplified MYC or liver metastases have an additional risk of not benefiting from checkpoint inhibitors and might have a significantly worse survival." (PMID 32110946, 2020). "Importantly, ABL1 and MYC mRNAs are correlated in melanomas from patients prior to treatment (left) and in the TCGA dataset, and an even more significant correlation was observed in paired samples from the same patients following relapse on BRAFi or BRAFi/MEKi (right)." (PMID 33122628, 2020). "Notably, at the protein level MYC appeared to be decoupled from MITF in ∼15–20% of metastatic human melanoma samples (n = 18) and melanoma cell lines (n = 7) reflected by a low MITF/MYC expression ratio in whole cell lysates as demonstrated in immunoblot analyses." (PMID 30651597, 2019). "The dependence of TFIIH-CAK on sequence-specific MITF and c-MYC constitutes a previously unrecognized mechanism feeding into super-enhancer-driven or other oncogenic transcriptional circuitries, which supports the concept of a transcription-directed therapeutic intervention in melanoma." (PMID 30651597, 2019). "Hence, a melanoma-specific demethylation mechanism that operates in a gene-dependent manner may compel the c-MYC, Sestrin-1, and SRPX2 transcripts to retain their introns, strongly suggesting an epigenetic control of splicing integrity." (PMID 30795533, 2019). "However, while SOX10 and MYC control a wide variety of cellular processes in melanoma cells, they have not been directly linked to endolysosomal trafficking." (PMID 26008978, 2015). "In addition, apoptosis, label-retention, frequency of ABCB5-positive cells and the expression of Wnt/β-catenin signaling target genes, MITF and c-MYC, were assessed in melanoma populations treated with compounds selected as either highly anti-clonogenic or highly cytotoxic." (PMID 24595456, 2014). "Ectopic co-expression of TS, IMPDH2, and PRPS2 cDNAs in MYC-depleted cells provided only a partial and short-term delay in proliferation arrest, indicating that still unidentified C-MYC target genes were required for MYC-dependent suppression of senescence in melanoma cells." (PMID 23249808, 2012). "Characterization of this animal model in combination with in vitro studies identifies c-MYC as a positive regulator of the pro-tumoral program elicited by TAMs, which is essential for establishing a microenvironment that supports the growth of melanoma and fibrosarcoma." (PMID 23028984, 2012). "However, there are also reports showing that a decrease of c-MYC level may sensitize human melanoma cells to cisplatin." (PMID 21324178, 2011). "First, CRISPR activation screens in melanoma cells identify functionally diverse regulators of TCR-specific cytotoxicity, including SAFB, KHDRBS1, MYC, CD44, WNT3A, WNT1 and others." (PMID 41946842, 2026). "The let‐7 family of miRNAs is frequently downregulated in melanoma, where it targets multiple oncogenes, including NRAS and MYC." (PMID 39823244, 2025).
melanoma (continued). "MITF and c-MYC, key melanoma transcription factors, regulate human DANCR expression and melanoma patients with high DANCR display significantly decreased survival." (PMID 41336739, 2025). "For instance, a study demonstrated that silencing c-MYC or its cofactor MAX with siRNA increased the responsiveness of melanoma cells to IFN-γ, while also enhancing the effector functions of T cells co-cultured with MYC-overexpressing cells." (PMID 40333779, 2025). "Our findings suggest that human melanoma cell lines can adopt two transcriptomically and phenotypically distinct, mutually exclusive “MITF-low” states—DEDIFF and MYC." (PMID 41405996, 2025). "The protein–protein interaction (PPI) network analysis identified hub genes such as MYC, BRCA1 and AURKB, which play critical roles in melanoma biology." (PMID 39823244, 2025). "The resulting activation of NOTCH-signaling results in the transcription of multiple oncogenes (c-MYC, PCNA, and CDK4) that promote melanoma progression." (PMID 40076754, 2025). "In melanoma A375and A2058 cells, the complex reduced chromatin binding of BRD4 inthe MYC promoter and inhibited cell proliferation(IC50 to 12.5 μM and 3 μM, respectively)." (PMID 41152016, 2025). "RI treatment led to the downregulation of CCND1, MYC, and BCL2 in proliferative cell lines, further supporting the role of NSD2 in melanoma progression." (PMID 40386826, 2025). "Mechanistically, ZWINT knockdown decreases the protein expression levels of c-MYC, MTOR, phosphorylated MTOR, pp38, and fibronectin, while c-MYC overexpression reversed the effects on melanoma cell proliferation and migration." (PMID 38950330, 2024). "One of the major functions of c‐MYC overexpression in melanoma progression is sustained inhibition of BRAF or RAS‐dependent cellular senescence, and when c‐MYC is lost or inhibited, it induces melanoma cellular senescence." (PMID 39161800, 2024). "LN metastasis requires that melanoma cells to undergo a metabolic shift towards FAO induced by MITF, a key transcription factor in MYC+MEL cells." (PMID 38065972, 2023). "In contrast, other long-term MEKi acquired resistance cells were highly dependent solely on ABL1/2, which stabilized MYC and ETS1 proteins in an ERK-independent manner, and induced β-catenin nuclear localization to drive melanoma survival." (PMID 36765910, 2023). "siRNA-mediated MYC knockdown decreased proliferation in FLC, and to a small extent in the melanoma line Colo741." (PMID 36692000, 2023). "In TNBC, upregulated MYC inhibits the MondoA-dependent activation of TXNIP to stimulate glycolysis, while in BRAF-mutant melanoma, the MYC-induced downregulation of the MondoA-TXNIP axis leads to vemurafenib resistance." (PMID 37443779, 2023). "MYC and MAPK1 are involved in cell cycle progression, apoptosis, and cellular transformation, and their over-expression is common in melanoma." (PMID 36339598, 2022). "All epigenetic drugs had a predominant inhibitory effect on the expression of the melanoma differentiation-related proteins MITF and SOX-10 and of the transcription factor MYC." (PMID 36397155, 2022). "An extra copy of chromosome 8q, containing the DGAT1 locus but also other putative melanoma oncogenes ASAP1/DDEF, MYC, and GDF6, has been observed in approximately 30% of melanoma cases." (PMID 35732120, 2022). "To further confirm that RAI14 affects c-MYC ubiquitination through FBXO32, we knocked down the expression of FBXO32 in RAI14 knockdown melanoma cells." (PMID 36233342, 2022). "Another crucial element influencing melanoma glycolysis is c-Myc, which is a member of the MYC proto-oncogene family (c-Myc, L-Myc, and N-Myc are collectively known as MYC) that encodes the helix-loop-helix leucine zipper (bHLHZip) transcription factor." (PMID 36620597, 2022). "We then treated RAI14 knockdown melanoma cells with MG132 and showed that protein expression of c-MYC was rescued." (PMID 36233342, 2022).
melanoma (continued). "Positive controls showed transcript expression for OCT4 on seminoma, SOX2 on melanoma, KLF4 on sweat glands, and c-MYC on normal colon." (PMID 33816543, 2021). "In melanomas, activation of the MAPK pathway increases transcription of HIF1α and v-MYC avian myelocytomatosis viral oncogene homolog (MYC)." (PMID 33396745, 2020). "In peripheral blood, a gene signature of 15 differentially expressed genes, which includes MYC and CDK2, is predictive and prognostic to anti-CTLA4 immunotherapy treatment and 1 year overall survival in melanoma patients." (PMID 31820036, 2020). "Most relevant molecular drivers that participate to melanoma metabolic plasticity include AKT, BRAF, p14ARF, MYC, NRAS, phosphatidylinositol-4,5-bisphosphate 3 kinase catalytic subunit α (PIK3CA) and phosphatase and tensin homolog (PTEN)." (PMID 32528879, 2020). "Western blot analysis of whole cell lysates confirmed the observed reduction in c‐MYC, GLUT1 and HK2 in sensitive melanoma cells." (PMID 31833658, 2020). "In contrast to c-MYC, the MCT4 gene (ENST00000581287.5) is herein presented to undergo an intron retention process not only in melanoma but also in BCC and SCC patients." (PMID 30795533, 2019). "It significantly reduced the transcript levels of LEF1, WNT10B, MITF-M, c-MYC and CCND1 and increased the mRNA levels of FZD7 and DKK1 in all melanoma cell populations." (PMID 27351373, 2016). "Here, we report successful generation of human iPSCs from terminally differentiated melanoma TILs that express high levels of PD-1 by Sendai virus- (SeV-) mediated transduction of the four transcription factors OCT3/4, SOX2, KLF4, and c-MYC." (PMID 27057178, 2016). "Here, we describe the derivation of human iPSCs from melanoma TILs expressing high level of PD-1 by Sendai virus-mediated transduction of the four transcription factors, OCT3/4, SOX2, KLF4, and c-MYC." (PMID 27057178, 2016). "In a recent example, Soengas and colleagues identified RAB7 as a new regulator of melanoma progression and showed this to be specifically wired into the melanoma lineage by the transcription factors SOX10 and MYC." (PMID 25670789, 2015). "To compare the predictions of signatures across platforms, we applied the E2F, MYC, and RAS signatures to the melanoma data set." (PMID 24244455, 2013). "Our finding that DANCR is directly regulated by both MITF and c-MYC may explain its high expression in both proliferative (MITF-high) and invasive (c-MYC-high) transcriptional states in melanoma." (PMID 41336739, 2025). "MYC appeared to have a substantial influence on immunotherapy resistance by negatively affecting Janus Kinase 2 (JAK2) expression and the responsiveness of melanoma cells to IFN-γ." (PMID 38139110, 2023). "Similarly, analysis of the melanoma TCGA dataset revealed that GREB1 gene expression was positively correlated with the expression of proliferative marker genes (CDK2, MYC, CCND1, and LIG1) and negatively correlated with CDKN1B." (PMID 37658191, 2023). "To confirm whether RAI14 regulated melanoma progression by targeting c-MYC, we overexpressed c-MYC in RAI14 knockdown melanoma cells." (PMID 36233342, 2022). "Consistently, DGAT1, ASAP1, MYC, and GDF6 are co-amplified in melanoma and other cancers." (PMID 35732120, 2022). "The cBioPortal database showed that MYC, NBN and KDR predicted poor survival of melanoma patients." (PMID 35688842, 2022). "Moreover, MYC and UBA2 expression was inversely correlated with the presence of CD8+ T cells in patients with melanoma, which is a predictive biomarker for the success of ICB." (PMID 35499080, 2022). "Together, these data suggest that neither MYC nor the mTOR pathway is a key driver of enhanced mitochondrial metabolism following CDK4/6 inhibition in melanoma cells." (PMID 33572972, 2021).
melanoma (continued). "Notably, the mTOR pathway can also activate fatty acid oxidation pathways; thus, we explored the role of MYC and mTOR signalling in metabolic reprogramming following CDK4/6 inhibition in the context of melanoma cells." (PMID 33572972, 2021). "In melanoma, MAPK and PI3K pathway activation induces glycolysis and its decoupling from the TCA cycle via stimulation of hypoxia-inducible factor 1α (HIF1α) and the v-MYC avian myelocytomatosis viral oncogene homolog (MYC)." (PMID 33498757, 2021). "Another limitation is that we have not confirmed the gene alterations of the three false-negative melanoma cases with a MYC or CDKN2A probes or a 5 or 7 color FISH probes, since the former probes are unavailable for us." (PMID 32393283, 2020). "Besides, the MYC gene was observed with CNV gains in more than 1/5 melanoma patients, which was not be reported before, implying a unique CNV status in Chinese melanomas." (PMID 32083130, 2020). "Intriguingly, reports also revealed that MYC could conversely modulate GLI1 transcription, suggesting a feedback loop of MYC-GLI1 in melanoma." (PMID 32732916, 2020). "Together, these observations delineate that MYC and CTNNB1 may act as immune exclusion molecules in MITF‐positive melanoma tumors." (PMID 32147909, 2020). "An inverse correlation (negative enrichment) of MYC targets and telomeres signature, as well as melanoma relapse gene expression signature were also observed (signature enriched in control cells)." (PMID 31110180, 2019). "Since c-MYC was unveiled as a protein partner of PRR11 and c-MYC gene was shown to undergo melanoma-specific intron retention, all five intronic miRNA target genes and some additional ones encoding selected protein interactors were, next, examined for intron retention incidents." (PMID 30795533, 2019). "Altogether, it seems that the c-MYC intron retention, together with the lack of c-MYC legitimate transcriptional activity, can serve as a novel and powerful biomarker for human melanoma versus BCC and SCC skin cancers." (PMID 30795533, 2019). "We include the data for MYC as an example for a gene generally showing higher mRNA expression levels in melanoma cells relative to non-transformed melanocytes." (PMID 30987032, 2019). "Providing that not just the one identified in the present study, but all the introns of each gene transcript (c-MYC, MCT4, Sestrin-1, and SRPX2) can be potentially retained in human melanoma, next, we attempted to map their intronic landscapes for protein encoding sequences." (PMID 30795533, 2019). "Moreover, MYC (log FC = −3.32), PPARG (log FC = 2.17), ZIC2 (log FC = 3.62) were also dysregulated in melanoma." (PMID 31681565, 2019). "However, in C8161 cells with concomitant KRAS/c-MYC dysregulation, TTM reversion of melanoma toxicity by DSF + OPT was diminished." (PMID 30792807, 2019). "This c-MYC-dependent triggering of intron retention presumably compels the Sestrin-1 and SRPX2 genes to undergo a similar process of noncanonical splicing, likely providing melanoma cells with certain survival, growth, and motility advantages." (PMID 30795533, 2019). "Knockdown of RTL1 in melanoma cells resulted in cell proliferation suppression; cell cycle arrest at G1 phase; and down-regulation of E2F1, CYCLIN D1, cyclin-dependent kinase 6 (CDK6) and c-MYC." (PMID 29285312, 2017). "To confirm that the effect of diclofenac on proliferation and MYC expression was not restricted to melanoma cells, we analysed its impact on the human histiocytic lymphoma cell line U937." (PMID 23874405, 2013). "Moreover, we constructed a miRNA–miRNA interaction network using the miRNet tool, revealing key regulatory genes in melanoma, including PLAG1, TGFBR2, CDKN2A, MAPK14 and MYC, which exhibited significant degrees and betweenness centrality in the network analysis." (PMID 39823244, 2025).